CD4 (CD4 molecule)
Diseases named in the same sentence as CD4 in open-access papers (continued):
Sharing a sentence is not in itself a finding about the gene and the disease.
influenza (continued). "Elicitation of CD4 T cells by influenza vaccines requires host HLA class II molecules to bind and present peptides derived from the H1, H3 and HA-B proteins." (PMID 32884842, 2020). "Because of the critical role that CD4 T cells play in protective antibody responses to influenza, here we have focused primarily on quantification of elicitation of CD4 T cells by the vaccines." (PMID 32884842, 2020). "Influenza infection increased the frequency of total CD4+ T cells in the BAL compared to mock infected controls." (PMID 33373420, 2020). "Infection elicits significantly stronger CD4+ responses compared to the influenza vaccine and thereby likely elicits better protection against reinfection." (PMID 32572168, 2020). "Adaptive transfer of effector CD4+ T cells isolated from mice infected with influenza lead to increased survival of recipient mice after influenza challenge." (PMID 32375274, 2020). "Conversely, CD4+ T cells possess a more complex role, which differentiate into Th1 or Th2 cells upon influenza infection, to activate B cells, stimulate antibody production, and express antiviral cytokines such as IFN-γ." (PMID 32370136, 2020). "Meanwhile, CD4+ helper T cells recognise the influenza peptides presented on MHC class II molecules on antigen presenting cells, such as B cells, macrophages and dendritic cells." (PMID 32788837, 2020). "There was a trend towards an association between protection from pneumonia or death and the presence of polyfunctional CD4+ T-cells at influenza diagnosis (83.3% [15/18] vs 53.8% [7/13]; p = 0.084)." (PMID 32572168, 2020). "The general frequencies determined for influenza-specific as well as autoreactive T cells were in line with previous results and ranged from 10 to 230 and 1 to 7 tetramer-positive cells per million CD4+ cells, respectively." (PMID 32423478, 2020). "Two CD4+ TCR structures have been solved in complex with HA306–318 presented by HLA-II molecules offering insight on how CD4+ TCRs can recognise influenza epitopes." (PMID 33374787, 2020). "Contrary to studies in South Africa from 2009 to 201111 and 2012–2016,29 the prevalence of influenza in the current study was higher among individuals with a CD4 count over 400 compared to those with a lower CD4 count." (PMID 33392051, 2020). "As expected, the number of cells reactive to our positive influenza peptide controls was higher, typically in a range of 20 to 1000 per million CD4+ T cells (median frequency 61 per million CD4+ T cells)." (PMID 32423478, 2020). "CD4 T cells also contribute to control of influenza infection, although depletion of this cell subset alone only slightly delayed viral clearance." (PMID 33603740, 2020). "By the way, our findings also showed a remarkable effect of Gln supplementation on immunosenescence, mainly in terms of the specific antibody response (IgM and IgA) against Influenza vaccination and the absolute number of effector CD4+ T cells." (PMID 33207604, 2020). "Patients with seroconversion to all three influenza vaccine strains were found to have higher CD38+CD4+ T cells pre-vaccination." (PMID 32012159, 2020). "IFNγ secreting CD4+ T cells can be generated against a range of influenza proteins, with immunodominant responses towards the Matrix 1 (M1) and Nucleoprotein (NP) of influenza viruses." (PMID 33374787, 2020). "A significant reduction in Tet+CD4+ T cells was seen in the spleen, however reductions in influenza specific CD4 and CD8 T cells in the lung and lung airways (BAL) did not achieve statistical significance." (PMID 33373420, 2020). "In another study, responders to influenza vaccination showed a higher frequency of Treg compared to non-responders, together with an elevated frequency of early differentiated CD4+ T cells and lower proportion of memory CD4+ cells." (PMID 33584708, 2020).
influenza (continued). "An additional explanation for our findings is that the complex viral protein composition of vaccines made from extracts of influenza virions in some way diminishes the CD4 T-cell and B-cell reactivity to the HA components in the vaccine." (PMID 32884842, 2020). "Unpublished studies by our laboratory indicated that IL-2 and IFN-γ production were the most readily quantified for influenza-specific CD4 T cells post vaccination." (PMID 32884842, 2020). "Here, we have assessed human CD4 T cell responses to a traditional egg-based influenza vaccine with recently available cell-derived vaccines and recombinant baculovirus-derived vaccines." (PMID 32884842, 2020). "As a strong Th1 T cell response is an integral part of the anti-influenza immune response, we assessed CD4+ and CD8+ T cells in the BAL, lung, LLNs, and spleen." (PMID 33373420, 2020). "Some CD4+ T cell populations in influenza-infected mice show evidence of perforin/granzyme-mediated cytolytic activity." (PMID 32375274, 2020). "Previous studies in human influenza challenge show a correlation between cytotoxic CD4+ T cells in peripheral blood preinfection and reduced disease severity." (PMID 31815739, 2020). "T-cell responses were assessed by analysing the frequencies of influenza-specific CD4+ and CD8+ T producing IFN-γ, IL-2, and TNF-α in PBMC harvested on days 1 and 22 from participants in groups MAP-FA-0, MAP-FA-15, MAP-UA-15, and IM-QIV-15." (PMID 32181756, 2020). "In conclusion, our study provides novel data on the cellular immune response to influenza in SOT patients, and shows that natural influenza infection elicited a significant increase in monofunctional and polyfunctional influenza-specific CD4+ T-cells." (PMID 32572168, 2020). "Another study mapped 41 healthy volunteer T cell responses to influenza before and during infection and demonstrated that influenza-specific CD4+ T cells correlate with disease protection against influenza challenge in humans." (PMID 32196410, 2020). "One report showed that the pre-existing cross-reactive memory CD4 specific to highly conserved internal influenza virus proteins are sufficient to alleviate influenza infection in a human inoculation model." (PMID 31019503, 2019). "Apparently, recipient mice with transferred BM CD4+ TSCMs secreted more influenza antibodies in serum." (PMID 30733641, 2019). "We found that, similar to autosomal-iSEXS scores, proportions of CD4+ T cells decreased in both males and females following influenza infection but rebounded in females earlier than males." (PMID 31722210, 2019). "Collectively, these studies have revealed a tremendous breadth in the CD4 T cell response to influenza that includes specificities derived from HA, NA, M1, NP, and the polymerase proteins." (PMID 31694141, 2019). "These mice, when infected with mouse adapted strains of influenza, show both a CD4+ and CD8+ T cell response, and thus have been used to study the role of CD4+ T cells in the activation of CD8+T cells." (PMID 30871179, 2019). "In the first two models, memory CD4 T cells specific for influenza were passively transferred to either wild-type (WT) or to Severe Combined Immunodeficient (SCID) mice that lack adaptive immune cells." (PMID 30641955, 2019). "Adults have been shown to have a broad and diverse influenza-specific CD4 T cell repertoire, with cytokine production enriched for IFNγ and typically considered to be “Th1-biased”22." (PMID 30692574, 2019). "Populations of influenza-reactive memory CD4+ T cells, on the other hand, have been repeatedly demonstrated to correlate well with protection in both younger and elderly adults." (PMID 30873150, 2019). "Influenza-specific CD4 T cell reactivity in these children was compared to young adult subjects with multiple past influenza encounters." (PMID 30692574, 2019). "Human influenza-specific CD4 T cells in adults produce abundant IFN-γ perhaps reflecting their original priming by infection." (PMID 31134060, 2019).
influenza (continued). "The preceding studies suggest that, although the human CD4 T cell repertoire is highly diverse with respect to reactivity to influenza viral proteins, understanding the specificity of CD4 T cells towards the HA protein is particularly important." (PMID 31694141, 2019). "Further investigations revealed increased frequencies of IFN-γ and/or TNF-α producing, influenza-specific CD4+ and CD8+ T cells in the lungs of infected pigs, resulting in an accumulation of memory cells in the lungs at 6 weeks post infection." (PMID 31539406, 2019). "We found that children had an overall lower frequency of influenza-specific CD4 T cells, most markedly to the internal virion protein NP." (PMID 30692574, 2019). "All strains of mice used in the current study elicited robust CD4 T cell responses to other viral proteins after influenza infection, including those specific for M1, NA, and NP." (PMID 31694141, 2019). "Experiments utilizing SCID hosts provide evidence that memory CD4 T cells alone can mediate this damage, which likely involves a highly specialized cytotoxic CD4 T cell subset observed in several models of influenza infection." (PMID 30641955, 2019). "At the level of the cellular response to antigens, DC responses and influenza-specific CD4+ and CD8+ T cell responses have been reported to be influenced by specific commensal microbiota." (PMID 31050747, 2019). "In accordance with our results, phase I clinical trials with split H5N1 vaccine or a vaccinia virus-based universal influenza vaccine candidate have also shown a prevalence of effector memory over central memory CD4+ T cell responses." (PMID 31766202, 2019). "CMI is critical for recovery from and memory against virtually all viral pathogens and natural influenza induces strong CD4+ and CD8+ T cell responses." (PMID 31166987, 2019). "This implies that early IIV immunizations establish a high frequency of HA-B-specific CD4 T cells, with this pattern reinforced further upon subsequent influenza exposures throughout life." (PMID 30692574, 2019). "Vaccination with the conserved CD4 T cell influenza-specific epitopes was able to elicit peptide-specific immune responses and T cell memory responses, which led to more rapid and robust induction of HA-specific antibody responses." (PMID 31683888, 2019). "Perhaps, with the transplantation of a small amount of CD4+ TSCMs from the donor BM, the anti-influenza immune of transplant recipients can be effectively improved to resist infection after BM transplantation." (PMID 30733641, 2019). "We and others have previously shown that the subset of CD4 T cells defined as circulating or pTfh cells are important determinants of immune response to influenza vaccines." (PMID 31100059, 2019). "In this manuscript we detailed differences in CD4 T cell specificity and function between a pediatric population with limited influenza exposures compared to young adults who likely have had multiple previous encounters with influenza virus." (PMID 30692574, 2019). "IL-2 producing CD4 T cells were used to quantify reactivity to influenza epitopes from spleen because in some strains of mice, this is the dominant cytokine expressed particularly in the spleen (and data not shown)." (PMID 31694141, 2019). "Overall, when we compared the relative contribution of CD4+ T cells and ILC2s to the population of type 2 cytokine expressing cells, it was apparent that CD4+ T cells were the major source of IL‐5 or IL‐13 in the early phase of influenza‐induced exacerbation." (PMID 29762870, 2019). "Using the 2017–18 LAIV formulation, a CD4+ IFNγ-positive or CD4+ IL2-positive T-cell response was seen in 55–68% of children to the influenza antigens tested, with approximately 80% of children showing a response to haemagglutinin or matrix and nucleoprotein." (PMID 31235405, 2019).
influenza (continued). "The cooperation of these two signaling pathways (IL-7 and IL-15 signaling) supported the residence of CD4+ TSCMs in the bone marrow and the recalling of CD4+ TSCMs in the influenza model." (PMID 30733641, 2019). "While an H5N1 WIV vaccine readily induced influenza-specific CD4+ T cells in human volunteers, split vaccine at the same antigen dose (2 × 7.5 μg HA) did not unless adjuvanted with AS03." (PMID 31766202, 2019). "A recent study suggests that CD4 T cells are involved in CD8 TRM development in the lung following influenza infection." (PMID 31552032, 2019). "Accordingly, the CD4 T cell responses to influenza vaccines have become focused in specificity and more limited in inflammatory response." (PMID 31134060, 2019). "Memory CD4 T cells provide potent secondary immunity to influenza infection in mice, but the scope of the antiviral mechanisms that they employ is still not clear." (PMID 30641955, 2019). "The studies reported here suggest that in the primary response to influenza infection, only subsets of the segments of HA are selected by the elicited CD4 T cell repertoire." (PMID 31694141, 2019). "After considering the ‘take’ of the donor cells, this transfer reconstitutes mice with a quantity of cells that is consistent with the total number of virus-specific memory CD4 T cells that can be detected in an influenza-primed mouse." (PMID 30641955, 2019). "Both biological and environmental factors can explain differences we observed between males and females in monocyte proportions and dynamics of CD4+ T cells in response to influenza infection." (PMID 31722210, 2019). "To evaluate for differences in influenza-specific CD4 T cell specificity and functionality between the pediatric and young adult populations, we enrolled a well-defined cohort of 10 pediatric subjects who were 2 years of age." (PMID 30692574, 2019). "The second important distinction between human influenza-specific B cells and CD4 T cells is the functional complexity of the elicited response to infection." (PMID 31134060, 2019). "In the study reported here, we analyzed the peptide epitope distribution of HA-specific CD4 T cells elicited by influenza infection from a panel of independent strains of mice." (PMID 31694141, 2019). "Because in these experiments also Th2 cytokine production by CD4+ T cells was increased, we conclude that both T cells and ILC2s play a role in influenza‐induced exacerbation of allergic airway inflammation, but with different kinetics." (PMID 29762870, 2019). "We next analyzed the differentiation status of influenza-specific CD4 T-cells before and after immunization." (PMID 31019503, 2019). "Overall, this study showed that both non-adjuvanted and adjuvanted formulations of the gH1-Qbeta vaccine induced influenza-specific CD4+ and CD8+ T-cell responses and influenza-specific induction of a number of cytokines including anti-viral IFN-γ." (PMID 30573748, 2018). "The enhanced response showed augmented levels of IFN-γ and IL-17 production from the M2e-specific CD4+ T cells, which are the cardinal features of strong heterosubtypic protection in the mouse model of influenza infection." (PMID 30271406, 2018). "We conclude that CD4 T cells of broad viral epitope specificity are recruited into the lung after influenza infection, where they then have the opportunity to encounter infected or antigen-bearing antigen-presenting cells." (PMID 29681900, 2018). "The influenza-specific cross-reactive CD4+ T-cell responses were investigated using separate CD4 external or internal peptide pools." (PMID 30131880, 2018). "Influenza infection of CD4 T cell-depleted mice resulted in a reduction of body weight similar to infected non-depleted mice (weight curve)." (PMID 29623077, 2018). "The vast majority of influenza-specific memory CD4+ and CD8+ T cells present within human lung tissue adopt a Trm phenotype." (PMID 29587436, 2018).
influenza (continued). "In young mice, the peak of CD4+ T cell numbers in the lung occurs just before flu viral clearance and results from effective priming by antigen presenting cells (APCs) leading to expansion of virus-specific effectors." (PMID 29616390, 2018). "Protection correlated with levels of cross-reactive but non-neutralizing antibodies of the IgG2a subclass, general increase of memory T cells and induction of influenza-specific CD4+ and CD8+ T cells." (PMID 30356772, 2018). "New roles continue to emerge of the key role influenza-specific CD4+ T cells play during heterologous infection." (PMID 29587436, 2018). "CD4+ T cells are important for generating high quality and robust immune responses to influenza infection." (PMID 29616390, 2018). "Mice treated with antibiotics before influenza infection showed a higher viral load in the lungs, reduced CD4+ T cells responses and reduced influenza specific antibody titers compared to control mice." (PMID 29483908, 2018). "Preexisting influenza-specific interferon (IFN)-γ-secreting CD4+ or CD8+ T cells can recognize conserved viral epitopes and provide cross-protection from heterosubtypic influenza A viruses, even in the absence of protective antibodies." (PMID 30131880, 2018). "Coincident with the diverse functions of CD4 T cells in immunity to influenza is their very broad epitope specificity." (PMID 29681900, 2018). "The current Trivalent Influenza Vaccine (TIV) is poor at eliciting CD4+ T-cell or CD8+ T-cell responses after vaccination, and much recent focus has been on finding an association between T-cell responses and influenza specific antibody responses." (PMID 30573748, 2018). "Upon restimulation by influenza-loaded DCs, low background responses were shown for all three parameters (namely, number of total splenocytes, percentage of CD4+ and CD8+ T-cell) in the sham-vaccinated mice." (PMID 29593719, 2018). "CD154 upregulation on CD4+ T cells after a 3 h influenza peptide stimulation of otherwise un-manipulated PBMC was used to identify influenza antigen specific CD4+ T cells." (PMID 30619245, 2018). "Protection against lethal challenge with influenza can be mediated by synergy of CD4 T effectors acting via generation of Ab and by perforin-mediated lysis due to ThCTL." (PMID 29632538, 2018). "Overall, influenza-specific CD4+ T cells are a cornerstone of effective influenza responses, and their role is a dynamic interplay on the recall of heterologous T and B cell responses and infection outcomes." (PMID 29587436, 2018). "Activation of CD4+ Th1-type cells by influenza vaccination induces the secretion of Th1-type cytokines (e.g., interferon-γ), which can activate macrophage phagocytosis and kill intracellular M. tuberculosis." (PMID 29460733, 2018). "We found that influenza-induced recruitment of mast cell progenitors to the lung was intact in Rag2−/− mice and mice depleted of CD4+ cells, implicating the involvement of innate immune signals in this process." (PMID 30337928, 2018). "Administration of the novel virus-like particle based vaccine elicited influenza-specific CD4+ and CD8+ T-cell responses and the induction of the cytokines IFN-γ, IL-17A, IL17F, IL-5, IL-13, IL-9, IL-10 and IL-21." (PMID 30573748, 2018). "Since CD4+ T cells are crucial for the plethora of responses to flu age-related changes in CD4+ T cells have vast effects on flu immune responses." (PMID 29616390, 2018). "For example, in mouse models of influenza infection, protection can be achieved by transfer of either CD4+ or CD8+ T cells alone." (PMID 29252098, 2018). "IL-2-dependent and -independent mechanisms have been described for generation of influenza-specific CD4 TRM cells, contributing to heterogeneity of protective TRM cells." (PMID 30147701, 2018). "An increase in frequency of CD154+CD69+CD45RO+CD38+ islet beta cell antigen specific CD4+ T cells was observed in subjects #1 and #2 14 days after influenza vaccination." (PMID 30619245, 2018).